CLCN7 (Cl-/H+ antiporter 7)
Description:
Slowly voltage-gated channel mediating the exchange of chloride ions against protons. Functions as antiporter and contributes to the acidification of the lysosome lumen and may be involved in maintaining lysosomal pH. The CLC channel family contains both chloride channels and proton-coupled anion transporters that exchange chloride or another anion for protons (By similarity). The presence of conserved gating glutamate residues is typical for family members that function as antiporters (By similarity).
Synonyms: ClC-7; OPTA2; CLC7; PPP1R63; HOD; OPTB4
Tractability: Small molecule: a structure with a bound ligand is known. Antibody: UniProt predicts a signal peptide or a membrane-spanning region. PROTAC: ubiquitination databases record sites on it; its protein half-life has been measured.
Gene: Protein-coding gene on chromosome 16 (1,444,934 to 1,475,104, reverse strand). Ensembl gene ENSG00000103249.
Subcellular location: Lysosome membrane
Pathways (Reactome):
Transport of small molecules: Stimuli-sensing channels
Gene Ontology:
Molecular function: protein binding; chloride channel activity; chloride:proton antiporter activity; chloride transmembrane transporter activity
Biological process: transepithelial chloride transport; chloride transmembrane transport; chloride transport; proton transmembrane transport; response to pH; transmembrane transport
Cellular component: chloride channel complex; lysosomal membrane; membrane; late endosome
Genetic constraint (gnomAD): Loss-of-function variants: 57 observed, 86.58 expected, observed/expected ratio (o/e) 0.66, 90% interval 0.53 to 0.82. The synonymous counts are far from expectation, so gnomAD's model fits this gene poorly and the ratio says little. Missense variants: 944 observed, 1,022.7 expected, observed/expected ratio (o/e) 0.92, 90% interval 0.87 to 0.97. Synonymous variants: 552 observed, 440.14 expected, observed/expected ratio (o/e) 1.25, 90% interval 1.17 to 1.35.
Gene-disease validity (ClinGen):
ClinGen rates the evidence that CLCN7 causes each of these diseases.
autosomal dominant osteopetrosis 2 (autosomal dominant): Definitive.
autosomal recessive osteopetrosis 4 (autosomal recessive): Definitive.
hypopigmentation, organomegaly, and delayed myelination and development (autosomal dominant): Definitive.
Homologues: Orthologues: chimpanzee CLCN7 (99% identical), macaque CLCN7 (99% identical), mouse Clcn7 (96% identical), rat Clcn7 (96% identical), guinea pig CLCN7 (95% identical), pig CLCN7 (93% identical), dog CLCN7 (85% identical), tropical clawed frog clcn7 (78% identical), zebrafish clcn7 (74% identical), Drosophila melanogaster ClC-b (46% identical), Caenorhabditis elegans clh-6 (45% identical). Paralogues in human: CLCN6 (42% identical), CLCN5 (29% identical), CLCN3 (29% identical), CLCN4 (28% identical), CLCN2 (23% identical), CLCN1 (22% identical), CLCNKB (20% identical), CLCNKA (19% identical).
Diseases named in the same sentence as CLCN7 in open-access papers:
CLCN7 is named in the same sentence as 84 diseases in open-access papers, as found by Europe PMC text mining. Sharing a sentence is not in itself a finding about the gene and the disease. The quoted sentences say what the papers report.
osteopetrosis (81 papers, 2010 to 2025). Osteopetrosis, also known as marble bone disease, is a descriptive term that refers to a group of rare, heritable disorders of the skeleton characterized by increased bone density on radiographs. "Our study expands the mutation spectrum of the CLCN7 gene and provides new insights into the pathogenesis of osteopetrosis." (PMID 40276109, 2025). "Given the patient's family history of osteopetrosis—his parents are first-degree cousins with a known CLCN7 gene mutation—a chest X-ray was performed, revealing diffuse thick bony sclerosis of the axial and appendicular skeleton, consistent with osteopetrosis." (PMID 40276691, 2025). "Biallelic variants result in severe osteopetrosis, while the most common defect in CLCN7 is a heterozygous missense variant." (PMID 40276109, 2025). "This is reminiscent of several dominant osteopetrosis-causing CLCN7 mutations, for instance R286Q and R762Q." (PMID 38838776, 2024). "The ClC-7 chloride (Cl−)-proton (H+) antiporter (also known as CLCN7) is localized to the endolysosomal compartments and mutations in CLCN7 lead to osteopetrosis and neurodegeneration." (PMID 38294065, 2024). "CLCN7 mutations cause the abnormal osteoclasts cannot secrete acid and thus cannot dissolve the bone, resulting in osteopetrosis." (PMID 40018371, 2024). "This study provides data on serum metabolomics in osteopetrosis caused by CLCN7 mutation and provides new potential metabolic markers and pathways for diagnosis and pathogenesis of osteopetrosis." (PMID 40018371, 2024). "These five pathogenetic HDV loci are associated with the susceptibility of osteopetrosis (CLCN7), hearing loss (GJB2), cardiomyopathy (PRDM16), arrhythmogenic right ventricular dysplasia 1 (TGFB3), and sucrase-isomaltase deficiency (SI), respectively." (PMID 38448908, 2024). "Only proteins in GP metabolism are predicted to interact with ClC-7, which increases our interest in the role of this pathway in the pathogenesis of osteopetrosis caused by CLCN7 mutation." (PMID 40018371, 2024). "To further understand the role of the screened three pathways in osteopetrosis caused by CLCN7 mutation, we analyzed the interactions of proteins in the three pathways with ClC-7 through the STRING database." (PMID 40018371, 2024). "Taken together, GP metabolism probably plays an important role in the pathogenesis of osteopetrosis caused by CLCN7 mutation." (PMID 40018371, 2024). "All of them, a total of 10 DEMs meet AUC>0.7, which means they have a certain accuracy for being the potential biological markers for osteopetrosis with CLCN7 mutation." (PMID 40018371, 2024). "We aimed to investigate the differences in the metabolome of osteopetrosis patients caused by CLCN7 mutation versus healthy controls (HC), uncovering potential subtype diagnosis biomarkers." (PMID 40018371, 2024). "To our knowledge, we demonstrated the serum metabolic profile of osteopetrosis caused by CLCN7 mutation for the first time." (PMID 40018371, 2024). "Depending on the type of mutation, CLCN7 mutations can lead to severe or relatively benign forms of osteopetrosis." (PMID 40018371, 2024). "CLCN7 LoF mutations entail osteopetrosis and, dependent on the degree of LoF, seemingly neuron- and kidney-specific lysosomal storage and neurodegeneration." (PMID 38838776, 2024). "In the absence of genetic testing or typical radiographic findings, elevated levels of lactate dehydrogenase (LDH), aspartate aminotransferase (AST), and creatine kinase BB isozymes (CK-BB) are associated with osteopetrosis caused by CLCN7 mutations." (PMID 40018371, 2024). "Variations in the CLCN7 gene are associated with different forms of osteopetrosis, including autosomal dominant osteopetrosis (ADO), autosomal recessive osteopetrosis (ARO), and the intermediate form." (PMID 38494246, 2024). "Our study also highlighted that metabolic disorder in GP metabolism probably involved in the pathogenesis of osteopetrosis caused by CLCN7 mutation." (PMID 40018371, 2024).
osteopetrosis (continued). "This study presented a comprehensive metabolomics evaluation for osteopetrosis caused by CLCN7 mutation in Chinese populations." (PMID 40018371, 2024). "Herein we identified novel variants, expanding spectrum of the TCRIG1 and CLCN7 genes and deepening our understanding of the relations between genotype and clinical characteristics of osteopetrosis." (PMID 36999084, 2023). "Mutations in the CLCN7 (chloride potential-dependentchannel 7) gene are responsible for 17 % of autosomalrecessive osteopetrosis cases and for the majority of autosomaldominant osteopetrosis cases (70 %)." (PMID 37465191, 2023). "In contrast to the gain-of-function variant p.Tyr715Cys, the impaired trafficking of CLCN7 in the dominant negative variant p.Gly215Arg (mouse p.Gly213Arg) results excess bone deposition and osteopetrosis." (PMID 37363915, 2023). "Seventy percent of the cases of autosomal dominant osteopetrosis are OPTA2, which is the most common form of osteopetrosis, and caused by a heterozygous mutation in the chloride channel 7 gene (CLCN7)." (PMID 37373559, 2023). "In our previous study, we investigated the causation of craniofacial bone and tooth dysplasia in osteopetrosis with CLCN7 mutations." (PMID 37373559, 2023). "Herein, we reported on four patients with osteopetrosis, in whom we identified compound heterozygous variants in the CLCN7 and TCIRG1 genes." (PMID 36999084, 2023). "Intriguingly, CLCN7 has been identified as the causative gene in a quite unique phenotype combining osteopetrosis, renal tubule acidosis, renal stones, epilepsy, and blindness." (PMID 35159175, 2022). "In terms of genetic characterization, biallelic mutations of the CLCN7 gene are reported to cause severe forms of osteopetrosis, showing bone damage, hematological failure and primary neurodegeneration, with symptoms resembling lysosomal storage defects." (PMID 33970241, 2021). "The second most frequent form of osteopetrosis (17% of ARO cases) is caused by mutations in the chloride voltage-gated channel 7 (CLCN7) gene." (PMID 33970241, 2021). "ADO2 is a typical human genetic disease, and dozens of studies have indicated that the mutation CLCN7 (R286W) is a disease-causing heterozygous mutation in many osteopetrosis families, and confirmed by Sanger Sequencing in our present study." (PMID 34702373, 2021). "As a member of the chloride channel family, there was a missense mutation in CLCN7 gene, accelerating the gating of the lysosomal Cl−/H−exchanger ClC-7/Ostm1, causing osteopetrosis with gingival hamartomas in cattle." (PMID 35011147, 2021). "To date, large-scale whole exome-sequenced studies of osteopetrosis have revealed more than 50 heterozygous mutations in the CLCN7 gene, which can lead to ADO2, among which the p.G215R has been studied extensively." (PMID 34702373, 2021). "Structure analysis revealed that the variant is located at the same "hot spot" as the most common CLCN7 mutations causing osteopetrosis." (PMID 33105733, 2020). "Mutations in the CLCN7 gene give rise to the complete spectrum of osteopetrosis phenotypes and are responsible for about 75% of cases of autosomal dominant osteopetrosis." (PMID 33105733, 2020). "The AD, AR and XL forms of osteopetrosis are predominantly caused by mutations in the CLCN7, TCIRG1 and IKBKG genes respectively." (PMID 31888683, 2019). "Here, we report a typical case of osteopetrosis in a 17.7-year-old male who carries a heterozygous c.746C>T mutation in exon 9 in the chloride voltage-gated channel 7 (CLCN7) gene." (PMID 30759959, 2019). "The mutations in CLCN7 have been associated with osteopetrosis in connection to the abnormal osteoclasts functions." (PMID 26829236, 2016). "It is possible that the dysplastic tooth and the impact of tooth germ in osteopetrosis patients or in Clcn7−/− mice are caused by the dysfunctional osteoclasts." (PMID 26829236, 2016).
osteopetrosis (continued). "Previously, we found that some osteopetrosis patients with CLCN7 mutations suffered from impacted teeth and root dysplasia." (PMID 26829236, 2016). "The mutations in the voltage-sensitive chloride channel genes CNCNKB, CLCN1, CLCN5, and CLCN7 have been linked to Bartter syndrome, myotonia congenita, Dent disease, and osteopetrosis, respectively." (PMID 25794116, 2015). "Mutations in OSTM1 (osteopetrosis associated transmembrane protein 1), coding for a protein involved in transport of ClCn7 to the ruffled border (and considered as a β subunit of ClCn7), have been described as causing severe osteopetrosis in ~5% of patients." (PMID 25873953, 2015). "In this study, the authors used whole-genome sequencing to map a new CLCN7 mutation that underlies a recessively inherited, severe form of osteopetrosis in Belgian Blue cattle." (PMID 24159188, 2014). "Like several human osteopetrosis-associated CLCN7 mutations, the present bovine CLCN7 mutation drastically accelerated ClC-7/Ostm1 gating." (PMID 24159188, 2014). "Because heterozygous Clcn7+/− mice suggest that osteopetrosis cannot be caused by CLCN7 haplo-insufficiency, these mutations are likely to exert a dominant effect." (PMID 24159188, 2014). "Some human osteopetrosis-causing CLCN7 mutations impair trafficking of ClC-7, resulting in retention of the mutant protein in the ER." (PMID 24159188, 2014). "Mutations in CLCN7 gene have been associated to the complete spectrum of osteopetrosis ranging from ARO to IRO and even to ADO type II." (PMID 25410126, 2014). "Whole-exome sequencing was also successfully employed to identify a human CLCN7 mutation in osteopetrosis patients." (PMID 24159188, 2014). "Taken together, these results – mainly the osteopetrosis in affected calves – strongly support the causality of the CLCN7 gene." (PMID 24159188, 2014). "Mutations in the CLCN7 gene have been associated with pathological phenotypes such as different types of osteopetrosis." (PMID 20830208, 2010). "Osteopetrosis, also known as osteosclerosis and marble-bone disease, is a rare genetic metabolic bone disorder caused by the dysplasia or dysfunction of osteoclasts, usually caused by variants of chloride voltage-gated channel 7 (CLCN7) gene." (PMID 40276109, 2025). "We therefore hypothesize that there was the same increased expression of the PCYT1A gene in osteopetrosis patients caused by CLCN7 mutation, which might account for the decrease level of phosphorylcholine." (PMID 40018371, 2024). "CLCN7 mutation caused abnormal osteoclasts, resulting in osteopetrosis." (PMID 40018371, 2024). "The mechanisms by which ADO-associated CLCN7 variants with accelerated gating cause osteopetrosis also remain unclear." (PMID 38838776, 2024). "In this study, we found that 10 metabolites including PGG2, Delta-12-prostaglandin J2 (D12-PGJ2), 15-KETE, PGB2, 6-Ketoprostaglandin E1, 13-oxo-ODE, LOOH, phosphorylcholine, acetylcholine and glycerophosphocholine, were significantly down-regulated in osteopetrosis patients caused by CLCN7 mutation." (PMID 40018371, 2024). "It is now widely accepted that the pathogenesis of CLCN7 mutations is due to the disruption of the acid environment necessary to dissolve the mineral component of bone, which prevents osteoclasts from functioning and leads to osteopetrosis." (PMID 40018371, 2024). "In addition, mutations in Clcn7, and its β-subunit Ostm1, also lead to osteopetrosis, severe retinal degeneration and neurodegeneration." (PMID 38294065, 2024). "The G215R allele of CLCN7, used here to reduce CLCN7 function in the mouse, was originally identified in a patient with dominant osteopetrosis which results from impaired osteoclast-mediated bone resorption and is thus physiologically quite different from the deposition defect in FIG4 mutants." (PMID 37363915, 2023). "CLCN7 gene mutations are involved in the pathogenesis of various forms of osteopetrosis." (PMID 36999084, 2023).
osteopetrosis (continued). "In addition, intermediate autosomal osteopetrosis (IAO) and the milder, autosomal dominant osteopetrosis type 2 (ADO2, or Albers-Schönberg disease) are caused by CLCN7 mutations." (PMID 33708769, 2021). "Various mutations in CLCN7 have been reported to be involved in the pathogenesis of osteopetrosis." (PMID 33304905, 2020). "Some studies suggested that CLCN7 mutations regulate bone formation in patients with osteopetrosis." (PMID 33304905, 2020). "Previous studies that reported several mutations in CLCN7 could result in severe recessive, dominant, and intermediate osteopetrosis." (PMID 33304905, 2020). "Interestingly, a heterozygous missense variant (c.1678A > G, p.Met560Val) in CLCN7 segregated with osteopetrosis among three affected patients." (PMID 33304905, 2020). "The severity of CLCN7-associated osteopetrosis is diverse, and the symptoms may range from asymptomatic to mild in ADO2 patients and may even be ARO with a very severe phenotype." (PMID 31412925, 2019). "Therefore, we focused on the known genes that result in osteopetrosis and found CLCN7 (chr16:g.1506174G>A) as a candidate mutation." (PMID 31412925, 2019). "We performed both SeV- and Epi5-mediated inductions from three patients who had disease-associated mutations in three different genes (TCIRG1, SNX10, and CLCN7) representing the diverse genetic heterogeneity of osteopetrosis phenotype and two healthy donors, under the same culture conditions." (PMID 31315669, 2019). "Previously we identified two Chinese osteopetrosis patients with CLCN7 gene mutations." (PMID 26829236, 2016). "Therefore, this study focused on osteopetrosis caused by CLCN7 mutations." (PMID 40018371, 2024). "However, the serum metabolic alterations in osteopetrosis caused by CLCN7 mutation are still unknown." (PMID 40018371, 2024). "This suggests that the differential metabolism characteristics of individuals can not only distinguish osteopetrosis patients and HC, but also have potential ability to further discriminate different osteopetrosis subtypes induced by biallelic or heterozygous mutations of CLCN7." (PMID 40018371, 2024). "Our data indicated that the mutation CLCN7 (R286W) may be a cause of the osteopetrosis family." (PMID 31412925, 2019). "Thus, patients with the CLCN7 mutation have reduced bone resorption, which leads to osteopetrosis." (PMID 30759959, 2019). "Among these, we highlight CLCN7, with an mLOF score of 0.549 for the recessive and 0.455 for the dominant forms of osteopetrosis (OPTB4 and OPTA2, respectively)." (PMID 40998763, 2025). "CLCN7-related osteopetrosis also manifests with dental abnormalities root dysplasia, tooth eruption disorder, dental hypoplasia, malformed teeth, and enamel dysplasia." (PMID 40276109, 2025). "CLCN7 is the gene that can not only cause severe recessive form of osteopetrosis, namely ARO, but also relatively benign form of osteopetrosis, namely ADO, depending on the type of CLCN7 mutation." (PMID 40018371, 2024). "In contrast to a more common form of ARO caused by variants in TCIRG1 encoding the a3 subunit of the vacuolar-type ATPases, CLCN7-related osteopetrosis is accompanied by lysosomal storage in neurons and the kidneys and can result in neurodegeneration." (PMID 38838776, 2024). "A third mouse model, in which the transport activity of ClC-7 is abolished (Clcn7td/td), manifests severe osteopetrosis as in Clcn7−/− mice but with less severe neurodegeneration." (PMID 38027030, 2023). "Disruption of CLCN7 expression results in severe lysosomal storage disorders that, in addition to osteopetrosis, can lead to neurodegeneration, including retinal atrophy." (PMID 36999084, 2023). "In the remaining ~30 % of cases, nomutations in the CLCN7 gene sequences were found, suggestinginvolvement of additional genes in the pathogenesisof this form of osteopetrosis." (PMID 37465191, 2023).